HOXB8 (homeobox B8)
Diseases named in the same sentence as HOXB8 in open-access papers (continued):
Sharing a sentence is not in itself a finding about the gene and the disease.
osteosarcoma (7 papers, 2019 to 2024). A usually aggressive malignant bone-forming mesenchymal neoplasm, predominantly affecting adolescents and young adults. "For example, HOXB8 deficiency suppresses osteosarcoma progression through inactivating Wnt/β-catenin signaling pathway." (PMID 31827394, 2019). "To further elucidate the mechanisms underlying CRC LLPS dependency in SE driven gene transcription, we conducted RNA‐seq after silencing HOXB8 in different osteosarcoma cell lines." (PMID 34432948, 2021). "The CRC calling algorithms of osteosarcoma predicted HOXB8 as a top candidate of CRC master TF with the highest IN and OUT degree index in chemoresistant and metastatic osteosarcoma." (PMID 34432948, 2021). "To further document the consequence of disruption of CRC phase separation on osteosarcoma, we stably suppressed HOXB8 expression using two distinct shRNAs (shHOXB8‐1 and shHOXB8‐2)." (PMID 34432948, 2021). "RNA‐seq analysis identified 653 deregulated genes upon HOXB8 depletion in both osteosarcoma cell lines." (PMID 34432948, 2021). "To determine the correlations between the HOXB8 expression status and chemo‐resistance, we stained for HOXB8 in osteosarcoma clinical specimens (n = 150) that comprised of specimens representing primary progression to chemoresistant disease and stratified them based on grade and histology." (PMID 34432948, 2021). "Next, the phase separation of HOXB8 was validated in osteosarcoma clinical specimens." (PMID 34432948, 2021). "Moreover, osteosarcoma patients with a high level of HOXB8 expression exhibited a lower overall survival and disease‐free survival than the patients with a low level of HOXB8 expression." (PMID 34432948, 2021). "Importantly, CRC LLPS inhibition via HOXB8 silencing impaired osteosarcoma cell proliferation, invasion, and sphere formation in 143B and SJSA1 cells." (PMID 34432948, 2021). "Moreover, overexpression of HOXB8 promoted osteosarcoma cell invasion." (PMID 34432948, 2021). "For instance, miR-196 inhibits the expression of Hoxb8, resulting in downregulation of Shh expression in mouse forelimb development, whereas its overexpression suppresses cell proliferation and migration by suppressing HOXA9 in human osteosarcoma cell lines." (PMID 33572377, 2021). "To explore whether the osteosarcoma metastasis correlated with CRC components expression, we analyzed HOXB8 expression data from gene expression omnibus databases." (PMID 34432948, 2021). "Notably, although GSK‐J4 targets HOXB8 to disrupt CRC phase separation, we cannot exclude the contribution of other targets to the therapeutic activity of GSK‐J4 in osteosarcoma." (PMID 34432948, 2021).
cervical cancer (5 papers, 2014 to 2023). A primary or metastatic malignant neoplasm involving the cervix. "In 2019, an investigation on cervical cancer and microRNA revealed that miR-32-5p can regulate cell proliferation by targeting HOXB8, homeobox B8, which encodes a nuclear protein with a homeobox DNA-binding domain." (PMID 37160545, 2023). "For example, HPV 16 deregulates miR-139-3p in HPV-associated cancers, HPV 16 E5 down-regulates miR-196a expression and up-regulated HoxB8, a target of miR-196a in cervical cancer." (PMID 31552174, 2019). "The MiR-32-5p/HOXB8 axis might serve as a potential target for the clinical diagnosis and treatment of cervical cancer." (PMID 36980210, 2023). "MiR‐32‐5p targets HOXB8 to repress the cellular malignant behavior in cervical cancer cells." (PMID 33448691, 2020). "However, instead, miR-32-5p could inhibit cellular malignant behavior by regulating the expression of HOXB8 in cervical cancer." (PMID 36980210, 2023).
colon cancer (5 papers, 2015 to 2023). "Conversely, hypomethylation and upregulated oncogene functions of HIST1H3I (Histone linker 1 with Histone H3.1), HIST1H3D (Histone linker 1 with Histone H3.D), NFATC4 (Nuclear factor of activated T-cells cytoplasmic 4) and HOXB8 (Homeobox B8) were associated with adiposity and colon cancer." (PMID 35629083, 2022). "In this study, we confirmed that neuroendocrine differentiated colon cancer cell-derived exosomes with an abundance of lnc-HOXB8-1:2 can be absorbed by tumor-associated macrophages in vitro; thus, the expression of lnc-HOXB8-1:2 increased in TAMs." (PMID 36030223, 2022). "lnc-HOXB8-1:2, derived from exosomes secreted by neuroendocrine differentiated colon cancer cells, was identified in our study." (PMID 36030223, 2022). "Our data showed that lnc-HOXB8-1:2 was abundant in neuroendocrine differentiated colon cancer cell-derived exosomes." (PMID 36030223, 2022). "Recently, HoxB8 was shown to promote the epithelial-to-mesenchymal transition and metastasis in gastric and colon cancers." (PMID 31137902, 2019). "Upregulation of HoxB8 was first described in human colon cancer." (PMID 31137902, 2019). "For instance, HOXB6, HOXB8 and HOXC9 are dysregulated at various stages of colon cancer development." (PMID 25875824, 2015).
leukemia (4 papers, 2008 to 2024). A malignant (clonal) hematologic disorder, involving hematopoietic stem cells and characterized by the presence of primitive or atypical myeloid or lymphoid cells in the bone marrow and the blood. "Hoxb8-FL cell–derived leukemia was almost fully penetrant in Cdkn2a-WT MYB::PLEKHO1, Cdkn2a-KO MYB-TR, and Cdkn2a-KO MYB::PLEKHO1 recipient mice but was rarely observed in other genotypes and only with significantly longer latency." (PMID 39499902, 2024). "We performed RNA-Seq and CUT&RUN for V5 in Hoxb8-FL.MS5 cells to determine how MYB fusions initiate leukemia in these cells." (PMID 39499902, 2024). "To investigate how BPDCN MYB fusions induce leukemic transformation of Hoxb8-FL progenitor cells, we performed CUT&RUN in MYB::PLEKHO1 leukemia cells using an anti-V5 antibody to detect chromatin occupancy of the exogenously expressed fusion protein." (PMID 39499902, 2024). "Hoxb8-FL cell–derived MYB-TR and MYB::PLEKHO1-driven leukemias were positioned between myeloid progenitors, monocytes, and DCs, consistent with their surface protein marker expression." (PMID 39499902, 2024). "While some leukemia clones showed reduced dTom expression levels, expression of GFP confirmed their derivation from transplanted Hoxb8-FL cells." (PMID 39499902, 2024). "Conversely, in our Hoxb8-FL system, MYB-WT caused impaired differentiation of hematopoietic progenitor cells but did not induce leukemia, while BPDCN-associated MYB fusions were able to initiate leukemia." (PMID 39499902, 2024). "In contrast to MYB-TR, MYB::PLEKHO1 did not require Cdkn2a KO to initiate leukemia in Hoxb8-FL cells." (PMID 39499902, 2024). "A caveat to these findings is that we cannot rule out that residual effects of the Hoxb8-ER transgene contribute to survival of these leukemia cells in vivo or that Hoxb8-FL cells may represent a nonphysiological hematopoietic progenitor state." (PMID 39499902, 2024). "In vivo transplantation of C/EBPα-K313-expressing Hoxb8 cells could not induce leukaemia." (PMID 34226527, 2021). "To investigate why MYB::PLEKHO1 but not MYB-TR initiated leukemia in Cdkn2a-WT Hoxb8-FL cells, we developed a system to culture MYB-expressing Hoxb8-FL cells in vitro without requiring Hoxb8 activation." (PMID 39499902, 2024). "This suggests that MYB-TR activates the G1/S cell cycle checkpoint and could explain why MYB-TR Hoxb8-FL.MS5 cells have a slow growth rate in vitro, and MYB-TR is unable to induce leukemia in vivo without KO of Cdkn2a." (PMID 39499902, 2024).
trichotillomania (4 papers, 2020 to 2024). A disorder characterized by repetitive pulling out of one's hair resulting in noticeable hair loss; the individual experiences a rising subjective sense of tension before pulling out the hair and a sense of gratification or relief when pulling out the hair. "The exact cause of trichotillomania is still not clear, but three mouse models (Hoxb8 KO, Sapap3 KO, and Slitrk5 KO) with elevated grooming behaviors have been developed to study the pathophysiology of trichotillomania." (PMID 36066198, 2022).
obsessive-compulsive disorder (3 papers, 2013 to 2020). A disorder characterized by the presence of persistent and recurrent irrational thoughts (obsessions), resulting in marked anxiety and repetitive excessive behaviors (compulsions) as a way to try to decrease that anxiety. "Already some recent exciting results have implicated microglia as the primary site of defects in Rett's syndrome, a model of autism spectrum disorders (ASD), and Hoxb8-deficiency, a model of obsessive compulsive disorder." (PMID 23720611, 2013). "Mutation of Homeobox B8 (Hoxb8, only expresses in the microglia in mice) in mice causes pathological grooming, hyperanxiety, and social impairment deficits, which are similar to the obsessive-compulsive disorder (OCD) and autism spectrum disorders (ASDs) observed in human." (PMID 32635937, 2020).
ovarian carcinoma (3 papers, 2016 to 2021). A malignant neoplasm originating from the surface ovarian epithelium. "Studies have found that HOXB4 is aberrantly expressed in ovarian cancer tissues and cell lines, compared with normal ovaries, while HOXB8 is associated with shorter survival in several independent ovarian cancer follow-up studies." (PMID 34930913, 2021). "Besides, overexpression of HOXB8 was significantly associated with OS among TCGA ovarian cancer patients (P = 0.038)." (PMID 34930913, 2021). "Many studies have found that HOXB cluster members are involved in the tumorigenesis or progression of ovarian cancer, including HOXB2, HOXB3, HOXB4, HOXB7, and HOXB8." (PMID 33815481, 2021).
colon adenocarcinoma (2 papers, 2021 to 2022). "In this study, we further illustrated that exosome-derived lnc-HOXB8-1:2 induced the migration and invasion of TAMs to promote the development of colon adenocarcinoma with neuroendocrine differentiation via sponging hsa-miR-6825-5p to upregulate CXCR3 expression." (PMID 36030223, 2022).
endometrial carcinoma (2 papers, 2019 to 2025). A malignant tumor arising from the epithelium that lines the cavity of the uterine body. "LINC03057 (also known as lnc-HOXB8-1:2 or RP11–357H14.17) is a lncRNA associated with the progression of different tumors, such as colorectal, gastric and endometrial carcinoma, with shortened overall survival and poor prognosis." (PMID 40863726, 2025). "Six HiChIP target genes (BRAP, RASGRP1, HOXB1, HOXB6, HOXB7 and HOXB8) were enriched for miRNA targets of MIR196A1, itself a HiChIP target gene, providing evidence to link these genes together in a potential network that may mediate the effects of endometrial cancer risk variation." (PMID 31561579, 2019).
esophageal squamous cell carcinoma (2 papers, 2013 to 2024). Esophageal squamous cell carcinoma (ESCC) is a type of esophageal carcinoma (EC) that can affect any part of the esophagus, but is usually located in the upper or middle third. "Deregulated expression of HOX genes including HOXB8, HOXC8, HOXD8 and HOXA7 in esophageal squamous cell carcinoma have been reported, and miR-196a is significantly up-regulated in pancreatic, breast, and esophageal cancer." (PMID 23967217, 2013). "Similarly, HOXB cluster dysregulation, and dysregulation of the HOX genes in general, are closely linked to cancer, though these specific genes (HOXB7, HOXB8, and HOXB9) have not been shown in specific relation to esophageal squamous cell carcinomas." (PMID 38886487, 2024).
lung carcinoma (2 papers, 2022 to 2025). "From this list, only the lung carcinoma (LUAD) had a similar correlation pattern between HOXB8 expression and monocyte and macrophage infiltration." (PMID 40619489, 2025).
renal carcinoma (2 papers, 2019 to 2021). A carcinoma arising from the epithelium of the renal parenchyma or the renal pelvis. "Of note, in renal cancer, HOXB8 is prognostic, with high expression depicted as favorable (Human Protein Atlas resource))." (PMID 34445617, 2021).
behavioral disorders (1 paper, 2021). "Since Hoxb8 is only present in approximately 40% of microglia, it is still unclear whether Hoxb8-related microglia have an important function in the maintenance of normal behavior or Hoxb8-negative microglia result in abnormal grooming in Hoxb8-related behavioral disorders." (PMID 33467014, 2021).
congenital heart disease (1 paper, 2017). A heart disease that is present at birth. "They hypothesized that the variant might have an impact on miR-196a-HOXB8-Shh signaling pathway, and therefore, be associated with congenital heart disease susceptibility." (PMID 29186852, 2017).
liver cancer (1 paper, 2017). An epithelial or non-epithelial malignant neoplasm that arises from the liver. "For examples, the dynamic expression of RARB, RARG similar with RARA can control the development and proliferation of liver cancer and HOXB8 from HOX family can play a prominent role as a brain tissue biomarker." (PMID 29033978, 2017).
lung adenocarcinoma (1 paper, 2025). A carcinoma that arises from the lung and is characterized by the presence of malignant glandular epithelial cells. "This suggests that HOXB6 and HOXB8 expression (in at least pancreatic and lung adenocarcinoma) enhance immunosuppressive effects of cancer cells by promoting immune evasiveness of macrophages and thereby contributing to an immunosuppressive microenvironment affecting macrophage differentiation." (PMID 40619489, 2025). "In this study, we have focused on analyzing HOXB6 and HOXB8’s effects on pancreatic (and lung) adenocarcinoma in vitro, we also used publically available data from a larger collection of tumor samples to verify gene expression, immune cell infiltration, and correlate to patient outcomes." (PMID 40619489, 2025). "Changes in immune evasion properties were also observed in a lung adenocarcinoma cell line upon reduction of HOXB6 and HOXB8 expression." (PMID 40619489, 2025).
metastatic colorectal cancer (1 paper, 2019). "Further investigation revealed that HOXB8 was a predictor of the effects of FOLFOX4 chemotherapy in metastatic colorectal cancer." (PMID 31787845, 2019).
metastatic tumors (1 paper, 2021). "The ratios of Ki67‐positive cells and the numbers of metastatic tumor cells were lowered in HOXB8 KD cell‐derived primary and metastatic tumors." (PMID 34432948, 2021). "CRC candidates, HOXB8, FOSL1, and HOXA9, were commonly and specifically associated with SEs in all chemoresistant and metastatic tumor samples." (PMID 34432948, 2021).
myeloid leukemia (1 paper, 2018). A clonal proliferation of myeloid cells and their precursors in the bone marrow, peripheral blood, and spleen. "Reduction of OPA1 mRNA expression, but not any of the other dynamin-like GTPases, was associated with a complete inability to release DNA with either differentiated human myeloid leukemia cells or mouse Hoxb8 neutrophils." (PMID 30054480, 2018).
neutropenia (1 paper, 2016). A decrease in the number of neutrophils found in the blood. "NE-deficient Hoxb8 progenitors were reconstituted with murine and human forms of typical NE mutants representative of SCN and cyclic neutropenia, and differentiation of the cells was analysed in vitro and in vivo." (PMID 27942017, 2016). "In our murine Hoxb8 model, induction of ER stress and the UPR, which has been suggested as the cause for the defects resulting in neutropenia in human patients, could be recapitulated during differentiation in cells reconstituted with mutant NE." (PMID 27942017, 2016).
Periodontal Disease (1 paper, 2020). "Therefore, this HoxB8 model system is an ideal tool to study the survival and inflammatory functions of neutrophils as well as the molecular mechanisms of their contribution to inflammatory diseases, including periodontal disease." (PMID 32630208, 2020).
periodontitis (1 paper, 2020). An acute or chronic inflammatory process that affects the tissues that surround and support the teeth. "Here, we describe a new perspective to analyze neutrophil contribution in the progression of periodontitis, using the recently developed in vitro HoxB8 system." (PMID 32630208, 2020). "Moreover, we aimed to establish a high-throughput platform for the identification of new therapeutic targets for the treatment of periodontitis by utilizing the HoxB8 in vitro model." (PMID 32630208, 2020).
peritonitis (1 paper, 2022). Inflammation of the peritoneum (tissue that lines the abdominal wall and covers most of the organs in the abdomen). "To further probe the dynamics of neutrophils generated in vivo from transplanted HoxB8-conditional progenitors, we first performed experiments using a model of sterile peritonitis induced by intraperitoneal injection of thiogylcollate." (PMID 35127689, 2022).
pneumococcal meningitis (1 paper, 2020). An acute purulent infection of the meninges and subarachnoid space caused by Streptococcus pneumoniae, most prevalent in children and adults over the age of 60. "Recently, using the HoxB8 system as well as in vivo in experimental pneumococcal meningitis, we and others demonstrated that, in the presence of E. coli-derived LPSs or in the context of E. coli or Streptococcus pneumoniae infection, the survival of PMNs was extended." (PMID 32630208, 2020).
Stroke (1 paper, 2025). Sudden impairment of blood flow to a part of the brain due to occlusion or rupture of an artery to the brain. "Both LGI1fl/Hoxb8+ and LGI1fl/Hoxb8− mice displayed nocifensive behaviours in response to brush stroke applied to the injured paw." (PMID 39301592, 2025).